SNORD82 (small nucleolar RNA, C/D box 82)
Synonyms: Z25; U82; RNU82
Gene: Small nucleolar RNA gene on chromosome 2 (231,460,371 to 231,460,440, reverse strand). Ensembl gene ENSG00000202400.
Gene Ontology:
Biological process: RNA processing
Cellular component: nucleolus
Homologues: Orthologues: chimpanzee SNORD82 (100% identical), macaque SNORD82 (96% identical), pig SNORD82 (89% identical), rat Snord82 (86% identical), dog SNORD82 (81% identical), mouse Snord82 (81% identical), rabbit SNORD82 (79% identical), guinea pig SNORD82 (74% identical), zebrafish SNORD82 (73% identical), tropical clawed frog SNORD82 (64% identical).
Diseases named in the same sentence as SNORD82 in open-access papers:
SNORD82 is named in the same sentence as 1 disease in open-access papers, as found by Europe PMC text mining. Sharing a sentence is not in itself a finding about the gene and the disease.
SNORD82 shares sentences with these, for which no sentence is quoted: tumor (1 paper).